SMG6 (SMG6 nonsense mediated mRNA decay factor)
Description:
Component of the telomerase ribonucleoprotein (RNP) complex that is essential for the replication of chromosome termini. May have a general role in telomere regulation. Promotes in vitro the ability of TERT to elongate telomeres. Overexpression induces telomere uncapping, chromosomal end-to-end fusions (telomeric DNA persists at the fusion points) and did not perturb TRF2 telomeric localization. Binds to the single-stranded 5'-(GTGTGG)(4)GTGT-3' telomeric DNA, but not to a telomerase RNA template component (TER). Plays a role in nonsense-mediated mRNA decay. Is thought to provide a link to the mRNA degradation machinery as it has endonuclease activity required to initiate NMD, and to serve as an adapter for UPF1 to protein phosphatase 2A (PP2A), thereby triggering UPF1 dephosphorylation. Degrades single-stranded RNA (ssRNA), but not ssDNA or dsRNA.
Synonyms: hEST1A; C17orf31; EST1A; KIAA0732; SMG-6; hSMG5/7a
Tractability: Small molecule: it has a binding pocket of medium quality. Antibody: its Gene Ontology location is reachable by antibodies, with high confidence. PROTAC: ubiquitination databases record sites on it; its protein half-life has been measured.
Gene: Protein-coding gene on chromosome 17 (2,059,839 to 2,303,785, reverse strand). Ensembl gene ENSG00000070366.
Subcellular location: Nucleus, nucleolus; Chromosome, telomere; Cytoplasm, cytosol
Subcellular location (Human Protein Atlas): Nucleoli; Basal body; Cytosol; Golgi apparatus; Plasma membrane; Primary cilium tip
Pathways (Reactome):
Metabolism of RNA: Nonsense Mediated Decay (NMD) enhanced by the Exon Junction Complex (EJC)
Gene Ontology:
Molecular function: DNA polymerase binding; protein binding; ribonucleoprotein complex binding; RNA binding; RNA endonuclease activity; telomerase RNA binding; telomeric DNA binding
Biological process: negative regulation of telomere capping; nuclear-transcribed mRNA catabolic process, nonsense-mediated decay; regulation of telomere maintenance; mRNA export from nucleus; regulation of dephosphorylation; regulation of telomere maintenance via telomerase
Cellular component: cytoplasm; cytosol; exon-exon junction complex; nucleolus; nucleus; telomerase holoenzyme complex; chromosome, telomeric region
Genetic constraint (gnomAD): Loss-of-function variants: 61 observed, 135.98 expected, observed/expected ratio (o/e) 0.45, 90% interval 0.36 to 0.56. The upper end of that interval is the gene's LOEUF score, 0.56, which puts it in group 2 of 6, group 1 being the genes least tolerant of losing a copy. Missense variants: 1,762 observed, 1,844.7 expected, observed/expected ratio (o/e) 0.96, 90% interval 0.92 to 0.99. Synonymous variants: 764 observed, 714.68 expected, observed/expected ratio (o/e) 1.07, 90% interval 1.01 to 1.13.
Homologues: Orthologues: chimpanzee SMG6 (98% identical), macaque SMG6 (97% identical), pig SMG6 (92% identical), rabbit SMG6 (91% identical), rat Smg6 (91% identical), mouse Smg6 (91% identical), guinea pig SMG6 (90% identical), tropical clawed frog smg6 (62% identical), zebrafish smg6 (53% identical), Caenorhabditis elegans smg-6 (19% identical), Drosophila melanogaster Smg6 (18% identical).
Diseases named in the same sentence as SMG6 in open-access papers:
SMG6 is named in the same sentence as 25 diseases in open-access papers, as found by Europe PMC text mining. Sharing a sentence is not in itself a finding about the gene and the disease. The quoted sentences say what the papers report.
coronary artery disease (3 papers, 2017 to 2022). "There was only evidence for differences in the prevalence of one variant in SMG6 between case and control groups for coronary artery disease in the UK Biobank." (PMID 34968759, 2022).
migraine (3 papers, 2023 to 2024). "Current progresses from genomic and proteomic studies have highlighted common pathogenic mechanisms underlying migraine and CKD involving vascular development and endothelial function, and loci mapping to genes CPS1 and SMG6 are found to affect both migraine and kidney function." (PMID 37306871, 2023). "Additionally, regions at chromosomes 14 and 17 contain the SERPINA1 and SMG6 genes, which were previously shown to be the closest genes to a lead migraine SNP." (PMID 36808568, 2023). "Additionally, among the overlapping genes between migraine and headache with glycemic traits, five genes have previously been associated with migraine (THADA, EHMT2, AMBRA1, and SMG6) and headache (ATG13); now, these genes are also implicated in glycemic traits." (PMID 36808568, 2023). "Furthermore, five of the 30 genome-wide significant genes overlapping migraine and more than one glycemic trait were the nearest genes to a lead migraine SNP (THADA, EHMT2, AMBRA1, and SMG6) and headache SNP (ATG13)." (PMID 36808568, 2023).
schizophrenia (3 papers, 2015 to 2019). A major psychotic disorder characterized by abnormalities in the perception or expression of reality. "ASIC2 was a computationally predicted interactor of the gene SMG6, structural variants in which have been associated with schizophrenia or bipolar disorder in a Spanish population." (PMID 31481665, 2019). "TOP2B2 peaks from untreated cells are associated with three genes (CNTN4, IMMP2L and SATB2) implicated in both autism and schizophrenia whilst TOP2B2 peaks from E2-treated cells are associated with five genes (CNTN4, IMMP2L, EPC, SMG6 and CACNA1C)." (PMID 26459242, 2015).
autism (2 papers, 2013 to 2015). Persistent deficits in social interaction and communication and interaction as well as a markedly restricted repertoire of activity and interest as well as repetitive patterns of behavior. "SMG6 encodes a protein that participates in the nonsense-mediated mRNA decay (NMD) pathway, and it was recently identified as an autism candidate gene by sequencing balanced chromosomal abnormalities in patients with autism or related neurodevelopmental disorders." (PMID 23597238, 2013).
epilepsy (2 papers, 2018 to 2022). A brain disorder characterized by episodes of abnormally increased neuronal discharge resulting in transient episodes of sensory or motor neurological dysfunction, or psychic dysfunction. "Intriguingly, the activity of the SMG6 promoter with the mutant allele at rs4523957 decreased by 22% in the dual‐luciferase assay, and up‐regulated expression of SMG6 was observed in an epilepsy rat model." (PMID 29363864, 2018). "Of the 30 protein coding genes with identified coding sequence or expression differences, ten had a prior association with seizure or epilepsy based on literature and database searches, including Aspa, Hic1, Nlrp1a, Nlrp1b, Pafah1b1, Smg6, Trpv1, Trpv3, Ywhae and 6330403K07Rik." (PMID 35606653, 2022). "Compared with control rats, the epilepsy model exhibited an approximate 52% increase (P = 0.006) in SMG6 mRNA expression, which is similar to the increase found for SMG6 protein (approximately 14%, P = 0.010)." (PMID 29363864, 2018). "In addition, multiple evidence from qPCR, ELISA and IHC analyses showed that the expression of SMG6 was consistently increased in an epilepsy rat model." (PMID 29363864, 2018). "To determine whether SMG6 is involved in epileptic activities, we established a rat epilepsy model based on a protocol involving PTZ induction." (PMID 29363864, 2018). "In addition, IHC confirmed the abnormal expression of SMG6 in the epilepsy model, indicating that hyperfunction of SMG6 is involved in epileptic seizures." (PMID 29363864, 2018).
Lissencephaly (2 papers, 2017 to 2019). A spectrum of malformations of cortical development caused by insufficient neuronal migration that subsumes the terms agyria, pachygyria and subcortical band heterotopia. "Deletions involving several of the highly differentiated genes in this region have been suggested to contribute to MDS, including PAFAH1B1 (the primary lissencephaly-related gene, also known as LIS1, CFA9:46,647,994–46,727,422), MNT (CFA9:46,466,709–46,482,614) and SMG6 (CFA9:46,161,531–46,405,748)." (PMID 28806925, 2017).
breast carcinoma (1 paper, 2023). "Within promoter regions, the top DEGs upregulated in EA was MAGI1, a junctional scaffold protein that acts as a tumor suppressor in the context breast cancer through inhibition of the p38 stress pathway, and SMG6, which has been implicated in DNA repair and telomere maintenance." (PMID 37732899, 2023).
colorectal cancer (1 paper, 2023). A primary or metastatic malignant neoplasm that affects the colon or rectum. "Genes implicated in the NMD pathway, such as Upf1, Upf2, Smg1, Smg6, and Smg7, are expressed in higher levels in colorectal cancer (CRCs) with microsatellite stability, and promote tumor growth in xenograft models." (PMID 37888706, 2023).
HIV-1 infection (1 paper, 2019). The type species of lentivirus and the etiologic agent of acquired immunodeficiency syndrome (AIDS). "To determine whether the expression of these proteins is modulated during HIV-1 infection, we assessed the levels of UPF1, UPF2 and SMG6 expression in HIV-1-infected primary MDMs using an HIV-1 reporter construct called NL4-3-Bal-IRES-HSA." (PMID 30732620, 2019).
leukemia (1 paper, 2020). A malignant (clonal) hematologic disorder, involving hematopoietic stem cells and characterized by the presence of primitive or atypical myeloid or lymphoid cells in the bone marrow and the blood. "In the ALD trials there were some clones showing clonal dominance with over-representation of the insertion site near SMG6, CCND2, and HMGA2, but this has not led to development of leukemia and may be transient, as was reported for a SIN LV vector used for treating β-thalassemia." (PMID 32322605, 2020).
Seizure (1 paper, 2018). A seizure is an intermittent abnormality of nervous system physiology characterized by a transient occurrence of signs and/or symptoms due to abnormal excessive or synchronous neuronal activity in the brain. "The significance of SMG6 hyperfunction in epileptic seizures deserves to be investigated in future studies." (PMID 29363864, 2018). "SMG6 is an element of the telomerase ribonucleoprotein complex responsible for telomere replication, but the association between SMG6 and epileptic seizures has not yet been determined." (PMID 29363864, 2018). "Some telomere abnormalities and nonsense mutations have been reported to be associated with seizures 19, 20, 21, but direct evidence of the role of SMG6 in epileptic seizures is lacking." (PMID 29363864, 2018).
Stroke (1 paper, 2024). Sudden impairment of blood flow to a part of the brain due to occlusion or rupture of an artery to the brain. "Next, using multitrait GWAS analysis (MTAG) on ACD and the prioritized traits (CAD, stroke, WMH), we identified intronic SNPs in SMG6 and ABCG8 to be GW significant (pMTAG < 1.67E‐08, for three phenotypes) for ACD." (PMID 39046104, 2024).
temporal lobe epilepsy (1 paper, 2018). A localization-related (focal) form of epilepsy characterized by recurrent seizures that arise from foci within the temporal lobe, most commonly from its mesial aspect. "In this study, we aimed to investigate the genetic roles of SRR and a neighbouring gene, nonsense‐mediated mRNA decay factor (SMG6), in temporal lobe epilepsy (TLE)." (PMID 29363864, 2018).
cancer (7 papers, 2008 to 2025). A tumor composed of atypical neoplastic, often pleomorphic cells that invade other tissues. "These genes were presumably involved in cancer (SMG6, HCK), cellular growth (CPVL), reproduction (ADGB, CRISP1, CTTNBP2NL, WDR78), and nervous system (AUTS2, CNTNAP2, CPVL, SRGAP2)." (PMID 40149444, 2025). "We also propose that SMG6 and TERT are novel molecular target candidates for LATS2-inactivated cancers such as MM." (PMID 36335095, 2022). "In cancers such as microsatellite instability (MSI) cancers, NMD has been shown, on the contrary, to be activated through increased expression of certain NMD-factor genes: UPF1, UPF2, SMG1, SMG6, and SMG7." (PMID 35052820, 2022).
tumor (5 papers, 2008 to 2023). "Expression levels for NMD-related factors (UPF1, UPF2, UPF3A, UPF3B, SMG1, SMG2, SMG6, and SMG7) were calculated from microarray-derived datasets of primary tumor samples (n = 40 MSI, n = 48 MSS) and matched normal colon samples (n = 95)." (PMID 30228267, 2018).
neurodevelopmental disorder (2 papers, 2013 to 2022). A behavioral and cognitive disorder with onset during the developmental period that involves impaired or aberrant development of intellectual, motor, or social functions. "For instance, loss-of-function mutations in UPF2, UPF3B, SMG8 and SMG9 genes, and CNVs targeting UPF2, UPF3A, SMG6, EIF4A3, RNPS1 and RBM8A genes, have been implicated in a variety of neurodevelopmental disorders, including DD, ID, ADHD and TAR syndrome." (PMID 35327467, 2022).
SMG6 also shares sentences with these, for which no sentence is quoted: bipolar disorder (2 papers); atherosclerosis (1); autism spectrum disorder (1); dyskeratosis congenita (1); Headache (1); malignant mesothelioma (1); melanoma (1); microcephaly (1); Obesity (1).